Y_RNA (Y RNA )
Gene: Miscellaneous RNA gene on chromosome 14 (55,651,534 to 55,651,634, forward strand). Ensembl gene ENSG00000200742.
Homologues: Orthologues: chimpanzee Y_RNA (100% identical), macaque Y_RNA (96% identical), dog Y_RNA (91% identical). Paralogues in human: Y_RNA (93% identical), RNY3 (92% identical), Y_RNA (92% identical), RNY3P1 (91% identical), Y_RNA (91% identical), Y_RNA (90% identical), Y_RNA (89% identical), RNY3P11 (88% identical), Y_RNA (88% identical), RNY3P14 (87% identical), Y_RNA (87% identical), RNY3P16 (86% identical), and 96 more.